TP53I3 (tumor protein p53 inducible protein 3)
Description:
Catalyzes the NADPH-dependent reduction of quinones, exhibiting a low enzymatic activity with beta-naphthoquinones and a strong preference for the ortho-quinone isomer (1,2-beta-naphthoquinone) over the para isomer (1,4-beta-naphthoquinone). Also displays a low reductase activity for non-quinone compounds such as diamine and 2,6-dichloroindophenol (in vitro).
Synonyms: PIG3
Tractability: Small molecule: a structure with a bound ligand is known; it has a high-quality binding pocket. PROTAC: ubiquitination databases record sites on it; its protein half-life has been measured.
Gene: Protein-coding gene on chromosome 2 (24,077,433 to 24,085,861, reverse strand). Ensembl gene ENSG00000115129.
Subcellular location (Human Protein Atlas): Vesicles
Gene Ontology:
Molecular function: quinone reductase (NADPH) activity; oxidoreductase activity
Biological process: apoptotic process; reactive oxygen species biosynthetic process
Cellular component: cytosol
Genetic constraint (gnomAD): Loss-of-function variants: 36 observed, 33.91 expected, observed/expected ratio (o/e) 1.06, 90% interval 0.81 to 1.4. The synonymous counts are far from expectation, so gnomAD's model fits this gene poorly and the ratio says little. Missense variants: 372 observed, 435.65 expected, observed/expected ratio (o/e) 0.85, 90% interval 0.78 to 0.93. Synonymous variants: 138 observed, 178.05 expected, observed/expected ratio (o/e) 0.78, 90% interval 0.67 to 0.89.
Homologues: Orthologues: chimpanzee TP53I3 (99% identical), dog TP53I3 (89% identical), pig TP53I3 (89% identical), rabbit TP53I3 (88% identical), macaque TP53I3 (82% identical), tropical clawed frog tp53i3 (68% identical), zebrafish TP53I3 (55% identical), Caenorhabditis elegans adh-1 (20% identical), Caenorhabditis elegans D2063.1 (20% identical), Caenorhabditis elegans sodh-2 (20% identical). Paralogues in human: VAT1 (30% identical), VAT1L (29% identical), CRYZ (28% identical), RTN4IP1 (27% identical), MECR (24% identical), PTGR3 (24% identical), ADH1B (23% identical), ADH1C (23% identical), CRYZL1 (23% identical), ADH1A (23% identical), ADH4 (23% identical), ADH6 (22% identical), and 5 more.
Diseases named in the same sentence as TP53I3 in open-access papers:
TP53I3 is named in the same sentence as 24 diseases in open-access papers, as found by Europe PMC text mining. Sharing a sentence is not in itself a finding about the gene and the disease. The quoted sentences say what the papers report.
papillary thyroid cancer (4 papers, 2020 to 2024). "There were experiments illustrating oncogenic role of TP53I3 in papillary thyroid cancer through activating the PI3K/AKT/PTEN pathway and in non-small cell lung cancer by promoting mitotic progression." (PMID 35493106, 2022). "TP53I3 is reported to be highly expressed in papillary thyroid carcinoma and plays oncogenic roles through the activation of the PI3K/Akt/PTEN pathway." (PMID 34362378, 2021).
breast tumor (2 papers, 2022 to 2023). "In ER+ breast tumor, we found that patients who did not respond to therapy showed a higher expression of TAP1 and TP53I3 compared with responders." (PMID 34109737, 2022).
gastric cancer (2 papers, 2022 to 2023). A primary or metastatic malignant neoplasm involving the stomach. "In summary, we first demonstrated that NOL6 can regulate the oncogenic behaviors of gastric cancer cells by down-regulating TP53I3 and up-regulating CDK4, MCM7." (PMID 35494047, 2022). "Studies had found that the expression of TP53I3 was generally decreased in gastric cancer tissues, and the up-regulation of TP53I3 inhibited the proliferation of tumor cells and induced apoptosis." (PMID 35494047, 2022).
lung adenocarcinoma (2 papers, 2021 to 2025). A carcinoma that arises from the lung and is characterized by the presence of malignant glandular epithelial cells.
ovarian carcinoma (2 papers, 2021 to 2024). A malignant neoplasm originating from the surface ovarian epithelium.
astrocytoma (1 paper, 2022).
brain tumors (1 paper, 2019).
colon cancer (1 paper, 2021). "For example, TP53I3 overexpression could elevate the colony formation, migration, and invasion ability of colon cancer cells." (PMID 34362378, 2021).
latent infection (1 paper, 2016). "The upregulation of transcripts of BBC3, GADD45A, MDM2, TP53I3, and downregulation of HEXIM1 during latent infection was confirmed as significant by RT-qPCR." (PMID 27898737, 2016).
liver steatosis (1 paper, 2025). "Steatosis severity was associated with upregulation of COL5A3 and TP53I3, whereas upregulated RASGEF1B, S100A12, and TGFBR3 were linked to early-stage liver steatosis." (PMID 40689242, 2025).
osteosarcoma (1 paper, 2023). A usually aggressive malignant bone-forming mesenchymal neoplasm, predominantly affecting adolescents and young adults.
prostate carcinoma (1 paper, 2017). A carcinoma that arises from epithelial cells of the prostate gland.
retinoblastoma (1 paper, 2024). A malignant tumor that originates in the nuclear layer of the retina.
cancer (10 papers, 2014 to 2025). A tumor composed of atypical neoplastic, often pleomorphic cells that invade other tissues. "Copy number variation in this repeat alters TP53I3 activation and probably affects an individual’s susceptibility to cancer." (PMID 26376692, 2015). "One of them, TP53I3 is a well-known example for tandem repeat instability associated with cancer." (PMID 26376692, 2015). "tp53i3 promotes the proliferation, migration, and invasion of cancer cells, and the downregulation of this gene promotes apoptosis." (PMID 40309513, 2025). "More and more studies have shown that TP53I3 can exhibit important effects in cancer cell biological behaviors." (PMID 34362378, 2021). "In recent years, several studies have suggested that TP53I3 may play an important role in various types of cancers." (PMID 34362378, 2021). "Although mutations in TP53I3 gene have not been identified in humans, a role for cancer predisposition of certain polymorphisms has been proposed." (PMID 24484525, 2014). "To date, there are no germline variants in TP53I3 associated with cancer risk." (PMID 33782397, 2021). "This subpopulation shows overexpression of TP53I3 and TAP1 correlated to multidrug resistance in human cancers and with the presence of hypoxic conditions." (PMID 34109737, 2022).
tumor (7 papers, 2013 to 2024). "These include alterations in e.g. MSH4, PRDM2, and TP53I3 in the MSI tumor as well as GATA, DOCK5, and IGSF11 in the MSS tumor." (PMID 28683819, 2017). "The results of GEPIA showed that the expression levels of CCT6A and FAP were increased in the tumor tissues of GC patients, and the expression levels of ZFP36 and TP53I3 were decreased in the tumor tissues of GC patients." (PMID 36010886, 2022). "We also found six tumor related genes, TUSC2, TP53I3, TSSC4, RAB23, RAB39A, and ERG, which function as either tumor suppressor genes or oncogenes." (PMID 24007313, 2013).
TP53I3 also shares sentences with these, for which no sentence is quoted: colorectal cancer (2 papers); glioblastoma (2); breast carcinoma (1); ganglioglioma (1); hepatocellular carcinoma (1); lung adenoma (1); melanoma (1); non-small cell lung carcinoma (1); steatosis (1).